MUC1 (mucin 1, cell surface associated)
Diseases named in the same sentence as MUC1 in open-access papers (continued):
Sharing a sentence is not in itself a finding about the gene and the disease.
cancer (1,230 papers, 1995 to 2026). A tumor composed of atypical neoplastic, often pleomorphic cells that invade other tissues. "In silico analysis suggested that MUC1 expression was associated with increased sensitivity of cancer cells to sunitinib." (PMID 41533164, 2026). "In clinical setting, MUC1 overexpression and genomic alterations were associated with significantly worse overall survival, cancer-specific survival, and recurrence-free survival confirming MUC1 as a survival-related prognostic factor in ccRCC." (PMID 41533164, 2026). "Considering that both MUC1 and miR-200c are associated with cancer progression and EMT, some authors investigated a possible correlation between them." (PMID 40001578, 2025). "With its unique patterns and cancer-associated epitopes, MUC1 has been studied as a potential therapeutic target for mucin-associated cancer cells." (PMID 40699805, 2025). "Three genes (FMNL3, LPCAT3, and MUC1) were significantly differentially expressed between primary tumors and metastases in TCGA pan-cancer and were associated with overall, disease-specific, and/or progression-free survival." (PMID 40162116, 2025). "This analysis revealed the strong expression of epithelial cell markers such as EpCAM and MUC-1 (approximately 70–60%), along with other cancer-associated markers, including TTF-1, Ki67, cytokeratin, and CD56." (PMID 39941799, 2025). "Specifically, studies have shown that the suppression of Core 1Gal-transferase (C1GT), which leads to significant reductions in MUC1 O-glycosylation, results in increased susceptibility to anoikis in MUC1-positive cancer cells." (PMID 40655139, 2025). "Another study shows that the cancer-associated Tn, T, and sialyl-Tn glycoforms of antigens such as MUC1 and CEACAM5." (PMID 40849468, 2025). "This design strategically utilizes cancer-associated MUC1 to enhance binding efficiency, thereby improving CAR-T cell activity against mucin-overexpressing cancer cells." (PMID 41372740, 2025). "To target a broader range of cancer-associated Tn antigens beyond Tn-MUC1, we incorporated tandem Helix pomatia agglutinin (HPA) lectins as the antigen-binding domain of the CAR." (PMID 41372740, 2025). "Due to MUC1′s differential expression in cancers and its association with cancer development and progression, it has been identified as a viable therapeutic target for BrCa." (PMID 41471303, 2025). "More specifically, alterations in the expression and glycosylation of MUC1 have been associated with the upregulation of pathways involving the cell proliferation, angiogenesis, migration, and invasion of cancer cells." (PMID 40699805, 2025). "This process is mediated by specific adhesion molecules, such as Mucin 1 (MUC1) on cancer cells, binding to Myelin-Associated Glycoprotein (MAG) on nerves, and interactions involving NCAM1 and β1 integrin." (PMID 40909268, 2025). "Our glyco-bridge was designed to engage the cancer-associated, cell surface mucin structure Tn-MUC1 with a single-chain variable fragment (scFv)." (PMID 41372740, 2025). "The glycopeptide PAHGVSSAPD prepared by this strategy is particularly noteworthy, as it constitutes part of the tandem repeat unit of a cancer‐associated mucin‐type glycopeptide Muc1 (with the glycosylated threonine replaced with serine in this case)." (PMID 39936247, 2025). "Recent studies have delved into the glycoforms of antigens, with a particular focus on the cancer-associated Tn glycoform of MUC1." (PMID 40849468, 2025). "The transmembrane O-linked glycoprotein mucin-1 (MUC1) has been extensively studied recently due to its overexpression in various cancer cells and use as a cancer antigen." (PMID 40649198, 2025). "Overexpression of MUC1 in cancer is caused by increased gene dosage and transcriptional levels, as well as a loss of posttranscriptional regulation." (PMID 40443562, 2025).
cancer (continued). "We thus generated E. coli optimized genes encoding for VNp fusions of a mAb against Muc1, a type I mucin that is misregulated in a variety of cancers, and is thus an attractive diagnostic biomarker." (PMID 39965660, 2025). "These alterations in MUC1 glycosylation are linked to cancer invasion, metastasis, angiogenesis, apoptosis, and immune surveillance." (PMID 40649198, 2025). "It was also demonstrated that MUC1 overexpression in cancer cells is associated with a heightened capacity for defense against natural killer cells, and that this process is regulated independently of MIC A/B." (PMID 40710292, 2025). "MUC1 is a multifaceted protein playing a seminal role in tumorigenesis and its expression has been linked to poor overall and disease-free survival in carcinomas of the breast, prostate, lung, stomach, and ovary." (PMID 40179083, 2025). "MMR deficiency was associated with high cytoplasmic MUC1 expression in MIPs, cribriform structures, and all carcinoma cells." (PMID 41332218, 2025). "MUC1 expression is dysregulated across pan-cancers and is associated with poor clinical outcomes; however, to date, there are no small molecules that target the oncogenic MUC1-C subunit." (PMID 38182558, 2024). "MUC1 has a significant role in immune cell signaling, which encourages the development of cancer linked to chronic inflammation." (PMID 38540735, 2024). "These unique traits of TA MUC1 lead to cell polarity loss and its localization over the entire surface of the cancer cell." (PMID 38611013, 2024). "MUC1 is a cancer-associated antigen that has been effective as a vaccine in preclinical animal models but showed limited immunogenicity and efficacy as a therapeutic vaccine in clinical trials in colon, breast, pancreas, prostate and lung cancer." (PMID 39450169, 2024). "Cancer-associated changes in the glycans of MUC1 and carcinoembryonic antigens were identified using this array." (PMID 39337716, 2024). "In cancer, abnormal expression of MUC1 is associated with cell adhesion, proliferation and invasion." (PMID 38627939, 2024). "For example, MUC1 under glycosylation is associated with more advanced disease in many types of cancer." (PMID 38539529, 2024). "The tumor‐associated glycoprotein Mucin 1 (MUC1) is aberrantly glycosylated on cancer cells and is considered a promising target for antitumor vaccines." (PMID 38344400, 2024). "First, we showed that the overexpression of MUC1 is sufficient to increase ccRCC proliferation, migration, and invasiveness, which are typical cellular features associated with cancer progression." (PMID 38254882, 2024). "Remarkably, robust and strong associations between VIM+ CAFs and MUC1+ cancer cell infiltration were found in both our chemotherapy cohort and TCGA‐STAD dataset." (PMID 39422697, 2024). "Overall, it is upregulated with glycosylation mutation in different cancer types, including breast cancer, myelomas, lymphomas, or pancreas cancers; hence, MUC1 becomes immunogenic." (PMID 39409876, 2024). "Mucin 1 (MUC-1) is an overexpressed glycoprotein and associated with cancer cell proliferation, migration and invasion in NSCLC." (PMID 36895477, 2023). "Co-expression network showed genes closely associated with RAC1 were calculated among which cancer genes such as MUC1, MUC20, CEACAM5, andCCL20 were positively correlated to expression of RAC1 whereas TIMP3 and MGP was negatively correlated." (PMID 37202394, 2023). "What events are associated with the appearance of anti-MUC1 antibodies, and do these antibodies contribute to successful immunosurveillance of MUC1+ cancers?" (PMID 37869082, 2023). "Multiple oncogenic signaling cascades (EGFR, CXCR4, FASN, P-gp, β-catenin, GSK-3B, STAT1, JAK2, MUC1, etc) are hallmarks of cancer cells that are associated with drug resistance, tumorigenic potential, and metastasis." (PMID 37151801, 2023).
cancer (continued). "CA 15-3 detects the proteolytically cleaved soluble form of Mucin 1 (MUC1) which in cancer cells are hypoglycosylated and with polarity loss, thereby acting as anti-adhesive molecules and enabling the detachment of malignant cells." (PMID 36938312, 2023). "The expression of MUC1 has been linked to cancer invasion and metastasis, as well as being seen as a biomarker that can distinguish between pre-cancerous and healthy tissue." (PMID 37958425, 2023). "The results revealed that mannosylated N-glycans of cancer-associated MUC1 were the most effective targets for the antibody-lectin sandwich assay." (PMID 37455827, 2023). "For example, binding of galectin-3 to TF on cancer-associated transmembrane mucin protein MUC1 increases cancer cell heterotypic adhesion to vascular endothelium and promotes endothelial secretion of metastasis-promoting cytokines such as GM-CSF and IL-6." (PMID 37612278, 2023). "SLea and SLex on MUC1 cover CAMs on the surface of cancer cells, thus causing cancer cells to lose adhesion, which has been confirmed in different cancers." (PMID 37894512, 2023). "Cancer cell-expressed MUC1 can be modified by multiple short, sialylated O-linked glycans, which can engage SIGLEC-9 and consequently induce calcium flux and MEK-ERK activation, leading to TAM-like phenotype." (PMID 36688997, 2023). "In cancer, the abnormal O-linked glycosylation of MUC1 can affect the interaction between MUC1 and lectins of the immune system." (PMID 36688997, 2023). "The expression of MUC1 has been shown to be significantly enhanced in cancers and is associated with metastatic potential and poor prognosis." (PMID 37444377, 2023). "The appearance of the cancer-associated carbohydrate T antigen on MUC1 mucin overexpressed in cancer cells, and the increased expression of galectin-3 are both typical features in various cancers." (PMID 37345016, 2023). "Various types of cancer are caused by abnormal glycosylation and overexpression of MUC1, a transmembrane glycoprotein found on the apical surface of epithelial cells." (PMID 36671915, 2023). "In PC cell lines (HPAF2 and Capan2), overexpressed MUC1 reversed cancer cell sensitivity to radiation, which was caused by MUC1-mediated elevations in glucose uptake and glycolytic flux." (PMID 36578477, 2022). "Anti-MUC1 antibodies mark another autoantibody found to be associated with several cancer types and appear to correlate with a more favourable prognosis." (PMID 35380164, 2022). "In this study, we evaluated the metabolomic profile of human ccRCC according to MUC1 expression and integrated it with transcriptomic data to associate the alterations in cancer metabolism with gene expression changes." (PMID 36430448, 2022). "When MUC1 is expressed on cancer cells, it is decorated by multiple short, sialylated O-linked glycans (MUC1-ST), which bind to Siglec-9 to induce macrophages to display a TAM-like phenotype with increased expression of PD-L1." (PMID 35418152, 2022). "In a study, a sandwich-type cytosensor based on the metal-organic framework (MOF) PCN-224 and tetrahedral DNA nanostructures (TDNs)-linked dual-aptamer (AS1411 and MUC1) was designed to assess cancer cells." (PMID 36195928, 2022). "The shorter and lower in density O‐glycan chains of cancer‐associated MUC1 facilitates reaching of even low levels of antibodies to the protein core of the MUC1." (PMID 34694686, 2022). "Structural differences between MUC1 isoforms associated with normal and cancer cells make it a highly considered target for cancer vaccination." (PMID 36307410, 2022). "Mucin 1 (MUC1) with the Tn epitope is a tumor associated antigen that is highly expressed on the surface of a variety of cancer cells." (PMID 35747139, 2022). "For this study, MUC1 tumour-associated antigen was chosen to be presented on the surface of the chimeric VLPs, as it is considered to be one of the promising targets for cancer vaccines." (PMID 35351156, 2022).
cancer (continued). "This seems to have a connection to the early discovery that expression of MUC1 is associated with progression of a variety of carcinomas." (PMID 35410995, 2022). "Together, these results confirm that the humanized anti-MUC1 antibodies CIM301-1 and CIM301-8 specifically recognize the cancer-associated MUC1 Tn epitope." (PMID 34070311, 2021). "MUC1 normally occurs on the apical surface of the cell membrane whereas, in cancer, overexpression and loss of polarity result in mucin presence circumferentially over the entire surface of the cell." (PMID 34206951, 2021). "The overexpression of the oncoprotein MUC1 correlates with the aggressiveness of malignant tumors and the poor survival of cancer patients and is associated with approximately 80% of human cancers." (PMID 33718192, 2021). "Aberrant overexpression of MUC1 has been linked to several human carcinomas contributing to the known characteristics of cancer cells, including EMT, stemness, resistance to anti-cancer treatments, epigenetic programming, and immune evasion." (PMID 33572108, 2021). "In patients without cancer but with a history of premalignant lesions (advanced colonic adenomas), a vaccine based on the tumor-associated antigen MUC1 was 30 to 40 times more immunogenic than the same vaccine in previous trials in cancer." (PMID 33827609, 2021). "Not only is MUC1 known to be overexpressed in most carcinomas, including ~90% of breast cancer tumors, but it is linked to immune evasion, cancer progression, and metastasis." (PMID 33532593, 2021). "In this study, we investigated the potential of fully humanized anti-MUC1 antibodies based on the murine 5E5 antibody that specifically recognizes MUC1 Tn/STn cancer-associated epitopes." (PMID 34070311, 2021). "Previously, the paradoxical roles of MUC1 based on its pattern of glycosylation in normal versus cancer cells have been reported in case of cancer-associated infections." (PMID 34070449, 2021). "In this light, Siglec-1 ligand was affinity captured from human breast cancer cell lines and identified as a glycoform of the common cancer-associated epithelial mucin MUC1." (PMID 34065256, 2021). "High expression of MUC1 has been linked to cancer cell proliferation, invasion, apoptosis, and transcription, and the downregulation of MUC1 in cancer cells inhibits cell migration and metastasis." (PMID 33718192, 2021). "MUC1 is a tumor-associated antigen with overexpression often associated with cancers, including colon, breast, ovarian, and pancreatic cancer." (PMID 33869742, 2021). "It has been stated that MUC1, with T antigen is natural ligand for Gal-3, and the interaction between galectin and cancer-associated MUC1 enhances adhesion of cancer cells to each other and to endothelial cells and, hence, promotes metastasis." (PMID 34681197, 2021). "At the end, we will discuss the crosstalk between the pro-angiogenic factors like VEGF and aberrant cancer-associated signaling pathways to address the potential utility of targeting MUC1 oncoprotein in therapeutic strategies." (PMID 33836774, 2021). "MUC1 is overexpressed in various types of cancer and implicated in multiple signaling pathways that enhancing cancer growth and maintenance." (PMID 34069461, 2021). "MUC1 with cancer-associated T antigen serves as a natural ligand of galectin-3 (Gal-3), a galactose-binding protein expressed inside cells, extracellularly (cell surface associated), and in the circulation." (PMID 34681197, 2021). "More interestingly, besides the brain, the interaction between MAG and cancer-associated MUC-1 is found to be sialic-acid dependent in pancreatic cancer perineural invasion." (PMID 34827170, 2021). "In Liu’s study, the researchers (including the authors of the current review) constructed nanoparticles to deliver an mRNA vaccine encoding the cancer-associated antigen MUC1 to dendritic cells (DCs) in lymph nodes, thus activating cancer-specific T cells." (PMID 35096628, 2021).
cancer (continued). "The identification of the cancer-associated Tn and STn glycoforms of MUC1 also lead to the introduction of the murine 5E5 antibody." (PMID 34070311, 2021). "C1GalT1-associated TF occurrence on MUC1 on cancer cells increases cancer cell interaction with galectins and promotes cancer cell progression and metastasis." (PMID 34944925, 2021). "High expression of MUC1 has been linked to cancer cell proliferation, invasion, metastasis, and apoptosis inhibition." (PMID 33718192, 2021). "Cancer-associated MUC1 inhibits dendritic cell (DC) maturation and promotes IL-10highIL-12low regulatory DC differentiation, which enables tumors to escape immune surveillance." (PMID 34681277, 2021). "It has been reported that interaction of cancer-associated TF on MUC1 with galectin-3 increases the interaction of MUC1 with EGFR on the cell surface." (PMID 34944925, 2021). "This part of MUC1 was reported to be involved in intracellular signal transduction through the interactions with several signaling molecules implicated in the cancer regulation by affecting the proliferation, apoptosis, and transcription of various genes." (PMID 34206951, 2021). "Mucin1 (MUC1) is a glycoprotein known as a tumor-associated antigen that is aberrantly overexpressed in several cancer cells." (PMID 33499388, 2021). "Carcinoembryonic antigen (CEA) and mucin 1 (MUC1) are widely expressed cancer antigens that are well-known to be associated with gastrointestinal malignancies, as well as extracolonic malignancies for which patients with LS are at risk." (PMID 34125344, 2021). "MUC1 itself has nine main splice variants in which MUC1/C, D and Z are associated with cancer progression." (PMID 32793288, 2020). "Their study demonstrated that the MUC1 (rs4072037) polymorphism is associated with risk of cancer in all genetic models (G vs. A; GA vs. AA; GG vs. AA; AG + AA vs. GG; GG vs. AG + AA)." (PMID 32660489, 2020). "The upregulation of MUC1 in cancer is a product of the aberrant O-linked glycosylation that lead to an increased sialylation of this protein." (PMID 32293552, 2020). "Antibodies binding to cancer-relevant glycopeptidic neoepitopes with higher specificities in carbohydrate recognition will be beneficial in the development of anti-MUC1 mAbs as therapeutic and diagnostic agents in the clinical settings." (PMID 33167508, 2020). "The expression of cancer-associated TF on MUC1 and its interaction with galectin-3 promote cancer cell adhesion to endothelium, encouraging thus directly cancer metastasis." (PMID 32280709, 2020). "The MUC1 cytoplasmic domain integrates multiple signaling pathways associated with cancer development and maintenance." (PMID 32486375, 2020). "Upon malignant transformation, many types of cancer cells express high levels of sialic acids and cancer-associated glycans (e.g., mucins (MUC1 and MUC16), Sialyl-Tn (sTn)) on their surfaces or secrete them to the extracellular media." (PMID 33333862, 2020). "The serum concentration of Gal-3 is increased in cancer patients, and Gal-3 enhances the homotypic aggregation of cancer cells and enables them to avoid anoikis by interacting with the cancer-associated mucin protein, MUC1." (PMID 31127200, 2020). "The most widely studied cancer–associated mucin is MUC1, which is overexpressed in a variety of cancers, especially breast and prostate cancers." (PMID 30952968, 2019). "The EV-based anticancer vaccine nanoparticle HDEA@EVAT was designed and developed by conjugating pH-sensitive DEAP, CD44 receptor-bound polysaccharide HA, TLR4-associated MPLA, and cancer-involved antigen MUC1." (PMID 30691225, 2019). "Binding of sialylated, cancer-associated MUC1 to Siglec-9 led to a polarization to M2 macrophages in vitro." (PMID 31552050, 2019). "Attempts to elicit humoral immune response to MUC1 peptides failed; yet chemoenzymatically synthesized MUC1 peptide with cancer associated O-glycan Tn and STn epitopes elicited a cancer-specific humoral response." (PMID 30911061, 2019).